DDAH1 (dimethylarginine dimethylaminohydrolase 1)
Diseases named in the same sentence as DDAH1 in open-access papers (continued):
Sharing a sentence is not in itself a finding about the gene and the disease.
psychiatric disorder (3 papers, 2021 to 2025). A disorder characterized by behavioral and/or psychological abnormalities, often accompanied by physical symptoms. "This disarrangement appears in the loss of expression level correlations between DDAH1 or DDAH2 and genes associated with psychiatric disorders and reduced functional similarity of DDAH1 or DDAH2 co-expressed genes in the patient groups." (PMID 36233204, 2022). "We found that correlations between expression levels of DDAH1 or DDAH2 and genes associated with mental illness are lost in cortical samples from psychiatric patients." (PMID 36233204, 2022). "This study’s objective was to estimate DDAH1 and DDAH2 associations with biological processes implicated in major psychiatric disorders using publicly accessible expression databases." (PMID 36233204, 2022). "Our results suggest a possible involvement of DDAH1 and DDAH2 in the pathophysiology of psychiatric disorders." (PMID 36233204, 2022). "Considering that the gene’s co-expression mirrors the similar biologic function of these genes, we attempted to compare DDAH1 and DDAH2 co-expression patterns in control subjects and patients with psychiatric disorders." (PMID 36233204, 2022).
inflammation (2 papers, 2018 to 2022). Aberrant reaction of the microcirculation characterized by movement of fluid and leukocytes from the blood into extravascular tissues. "Increased lung ADMA levels and decreased DDAH expression were observed in allergen challenge-induced airway inflammation animal models, and overexpression of DDAH1 could attenuate airway inflammation induced by ovalbumin, agricultural organic dust extract, or house dust mites." (PMID 36242005, 2022).
DDAH1 also shares sentences with these, for which no sentence is quoted: hepatocellular carcinoma (4 papers); bronchopulmonary dysplasia (2); coronary heart disease (2); Insulin resistance (2); ischemic stroke (2); Renal insufficiency (2); thrombosis (2); adenocarcinoma (1); anemia (1); bacterial infection (1); benign tumors (1); choroidal neovascularization (1); COVID-19 (1); diabetes (1); diabetic cardiomyopathy (1); diffuse intrinsic pontine glioma (1); Duchenne muscular dystrophy (1); esophageal tumors (1); fibrosis (1); head and neck tumor (1); hemorrhage (1); hyperlipidemia (1); hypoxia (1); lung carcinoma (1); Lung Injury (1); nasopharyngeal carcinoma (1); neurodegenerative disease (1); neurodevelopmental disorder (1); obsessive-compulsive disorder (1); Onset (1).
A further 10 diseases each share a sentence with DDAH1 in 1 paper.